SLC16A2 (solute carrier family 16 member 2)
Description:
Specific thyroid hormone transmembrane transporter, that mediates both uptake and efflux of thyroid hormones across the cell membrane independently of pH or a Na(+) gradient. Major substrates are the iodothyronines T3 and T4 and to a lesser extent rT3 and 3,3-diiodothyronine (3,3'-T2). Acts as an important mediator of thyroid hormone transport, especially T3, through the blood-brain barrier (Probable). Mediates the efflux of 3,5-diiodo-L-tyrosine (DIT) and 3-iodo-L-tyrosine (MIT).
Synonyms: MCT 8; MCT 7; MCT7; MCT8; XPCT; DXS128E; AHDS; DXS128; MRX22
Tractability: Antibody: UniProt places it where antibodies can reach, with high confidence; its Gene Ontology location is reachable by antibodies, with high confidence; UniProt predicts a signal peptide or a membrane-spanning region; the Human Protein Atlas places it where antibodies can reach. PROTAC: its protein half-life has been measured.
Target class: SLC16 family of monocarboxylate transporters; Electrochemical transporter; SLC superfamily of solute carriers; Transporter
Gene: Protein-coding gene on chromosome X (74,421,383 to 74,533,918, forward strand). Ensembl gene ENSG00000147100.
Subcellular location: Cell membrane; Apical cell membrane
Subcellular location (Human Protein Atlas): Plasma membrane
Pathways (Reactome):
Transport of small molecules: Organic anion transport by SLCO transporters
Gene Ontology:
Molecular function: amino acid transmembrane transporter activity; identical protein binding; protein binding; thyroid hormone transmembrane transporter activity; monocarboxylic acid transmembrane transporter activity; carboxylic acid transmembrane transporter activity; transmembrane transporter activity
Biological process: amino acid import across plasma membrane; amino acid metabolic process; negative regulation of neural precursor cell proliferation; thyroid hormone metabolic process; thyroid hormone transport; transport across blood-brain barrier; monocarboxylic acid transport; carboxylic acid transmembrane transport; transmembrane transport
Cellular component: apical plasma membrane; plasma membrane
Gene-disease validity (ClinGen):
ClinGen rates the evidence that SLC16A2 causes each of these diseases.
Allan-Herndon-Dudley syndrome (X-linked): Definitive. A syndrome with neuromuscular involvement characterized by infantile hypotonia, muscular hypoplasia, spastic paraparesis with dystonic/athetoic movements, and severe cognitive deficiency.
Homologues: Orthologues: chimpanzee SLC16A2 (99% identical), macaque SLC16A2 (99% identical), rabbit SLC16A2 (97% identical), mouse Slc16a2 (94% identical), rat Slc16a2 (94% identical), guinea pig SLC16A2 (93% identical), pig SLC16A2 (93% identical), dog SLC16A2 (91% identical), tropical clawed frog slc16a2 (57% identical), zebrafish slc16a2 (41% identical), Drosophila melanogaster Mct1 (20% identical), Drosophila melanogaster CG8468 (19% identical), and 11 more. Paralogues in human: SLC16A10 (47% identical), SLC16A8 (21% identical), SLC16A3 (21% identical), SLC16A9 (20% identical), SLC16A11 (20% identical), SLC16A5 (19% identical), SLC16A1 (19% identical), SLC16A7 (19% identical), SLC16A12 (18% identical), SLC16A14 (18% identical), SLC16A13 (17% identical), SLC16A6 (17% identical), and 1 more.